MGMT (O-6-methylguanine-DNA methyltransferase)
Diseases named in the same sentence as MGMT in open-access papers (continued):
Sharing a sentence is not in itself a finding about the gene and the disease.
glioma (continued). "Sensitivity of glioma cells to TMZ has been reported to be significantly involved in the level of MGMT repair activity in cells." (PMID 25625235, 2015). "Noteworthy, MGMT expression has been found heterogeneous within histological sections of gliomas, being higher in the inner core of the tumor than in the periphery." (PMID 26035292, 2015). "IMP3 expression was significantly associated with the absence of mutations of IDH1 gene (P = 0.0001) and with the unmethylated phenotype of MGMT in high-grade gliomas (P = 0.004)." (PMID 25695077, 2015). "The level of MGMT expression positively correlates with in vitro and in vivo glioma resistance to TMZ and bis-chloroethylnitrosourea." (PMID 25625235, 2015). "In relation to molecular characteristics of high-grade gliomas, we correlated IMP3 protein expression with IDH1 mutational and MGMT methylation status." (PMID 25695077, 2015). "Histone acetylation and methylation has been extensively investigated in relation to MGMT expression, in different cancer models including gliomas." (PMID 26035292, 2015). "The majority of IDH1 mutant high-grade gliomas also have MGMT promoter methylation, and IDH1 mutation is a stronger prognostic biomarker than MGMT promoter methylation." (PMID 26646075, 2015). "As already shown in clinical trials in patients affected by glioma that have been treated with the alkylating drug temozolomide, whose response to therapy is significantly ameliorated when MGMT expression is reduced because of promoter methylation." (PMID 26035292, 2015). "Further, immunofluorescence analysis on human tumour tissues showed co-localization of nuclear β-catenin and MGMT in subtypes of colon cancer, glioma, medulloblastoma and neuroblastoma." (PMID 26603103, 2015). "Due to its efficacy as a prognostic and predictive tumor marker, the assessment of MGMT promoter methylation status has become one of the most requested analyses for gliomas." (PMID 25823555, 2015). "ZEB1, an EMT inducer, was recently shown to be key in linking glioma stemness, invasiveness, and the expression of the chemoresistant enzyme O-6-methylguanine DNA methyltransferase (MGMT)." (PMID 25605251, 2015). "MGMT repairs O6-methylguanine DNA damage that is induced by alkylating agents such as temozolomide (currently the mainstay of anti-glioma chemotherapy), and strategies to overcome this resistance have been the focus of many studies." (PMID 25908947, 2015). "MGMT-mediated removal of alkyl groups from O6-MG is also relevant in alkylating chemotherapy of glioma, such as with temozolomide and nitrosourea derivatives." (PMID 26035292, 2015). "Of note, histone acetylation and the expression levels of HDAC are therefore increasing in relation to the regulation of expression of MGMT, consequently improving the response to therapy and the overall prognosis of patients affected by glioma." (PMID 26035292, 2015). "All these pieces of evidence prompted investigations on the relation between MGMT promoter methylation and the response to chemotherapy with alkylating drugs in patients affected by gliomas." (PMID 26035292, 2015). "Methylation of MGMT gene promoter was more frequently found in GBMs than in grade III gliomas (P < 0.0017 by Chi-square) and it was significantly associated with better OS and DFS in GBM (P < 0.0001 and P = 0.0001, resp)." (PMID 25695077, 2015). "The strong co-occurrence of MGMT, Temozolomide and methylation extracted by PALM-IST clearly indicates crucial association of them with Glioma." (PMID 25989388, 2015). "Especially, the associations of MGMT expressions or methylation status of the MGMT gene with the sensitivity to temozolomide have been well established in human glioma cells." (PMID 29061940, 2015). "Similar to the previous observations, we notice that three glioma cells exhibited undetectable MGMT mRNA expression in the absence or presence of TMZ (Unpublished observations of Chai et." (PMID 25337721, 2014).
glioma (continued). "Methylation of the promoter of the MGMT gene in gliomas allows for the prediction of the response to alkylating agents." (PMID 24699908, 2014). "According to previous researches, O6-methylguanine-DNA methyltransferase (MGMT), which causes the replication of DNA and the growth of malignant gliomas via removal of the alkylating lesion at the O6 position of guanine, may partially contribute to glioma resistance to TMZ therapy." (PMID 25373737, 2014). "In gliomas, IDH1 mutation, 1p/19q co-deletion, and MGMT promoter methylation can be routinely assessed and the results of these analyses help to refine the diagnosis and prognosis, and improve the treatment of the affected patients." (PMID 24559763, 2014). "Further studies for testing EB1 in addition to other biomarkers such as MGMT status and IDH1 mutation are warranted in patients with GBM and other high grade gliomas to confirm EB1 prognostic role." (PMID 25473893, 2014). "MGMT expression also varies between adult and paediatric gliomas; whereas more than 85% of paediatric patients demonstrate normal or low MGMT levels, in adult tumours only 50% show low MGMT expression." (PMID 25026297, 2014). "The potential of the MGMT-kB1-LODN to enhance cell killing was studied in vitro using two glioma cell lines (T98G and U87) and a melanoma cell line (A375P)." (PMID 25460932, 2014). "MGMT promoter methylation is a stronger prognostic factor than age, stage, and tumor grade for gliomas." (PMID 24959746, 2014). "The MGMT promoter methylation status has become a parameter for stratification of patients with glioma within several clinical trials." (PMID 24699908, 2014). "In gliomas, several molecular biomarkers including IDH mutation, 1p/19q co-deletion, and MGMT promotor methylation status have been introduced into neuropathological practice." (PMID 24559763, 2014). "A previous study has shown that the use of siRNA to transiently transfect nasopharyngeal carcinoma cells and glioma cells results in the inhibition of MGMT gene expression and increased sensitivity to bis-chloroethylnitrosourea." (PMID 25295108, 2014). "The MGMT methylation status of the LN18 and LN229 glioma cell lines as measured by MSP revealed an unmethylated MGMT promoter (MGMT active) for LN18 cells and a methylated MGMT promoter (MGMT inactive) for LN229 cells." (PMID 25061500, 2014). "MGMT expression status has been extensively studied and has prognostic and predictive significance in gliomas." (PMID 25026297, 2014). "Exogenous expression of the repair enzyme MGMT inhibited induction of autophagy in these glioma cultures while inhibition of MGMT led to an increase in autophagy." (PMID 24287492, 2013). "This is in contrast with a previous observation by unsupervised clustering analysis of the DNA hypermethylation profiles in 154 primary gliomas; of the three identified methylation patterns, Class 1 contains both the MGMT and EMP3 genes." (PMID 24083241, 2013). "MGMT was successfully inhibited in TMZ-resistant glioma cultures, enhancing sensitivity to TMZ for tumors implanted into the flanks of nude mice." (PMID 24287492, 2013). "The global methylation pattern in glioma patients remains stable upon tumor progression and recurrence, as previously reported for other genes, for instance MGMT." (PMID 24083241, 2013). "In several studies the role of MGMT methylation as molecular marker for overall survival of glioma patients treated with alkylating agents is discussed." (PMID 24380367, 2013).
glioma (continued). "Four tSNPs were detected to be associated with glioma by model association analyses including rs6010620 and rs2297440 in the RTEL1 gene, rs12022378 in the DCLRE1B gene, and rs12917 in the MGMT gene." (PMID 23683922, 2013). "All these effects were completely abrogated in isogenic glioma cells expressing O6-methylguanine-DNA methyltransferase (MGMT), indicating that a single type of DNA lesion, O6-methylguanine (O6MeG), is able to trigger all these responses." (PMID 23383259, 2013). "We also observed an inverse correlation between the level of MGMT and miR-221 expression in glioma cell lines." (PMID 24147153, 2013). "O6-methylguanine-DNA methyltransferase (MGMT) repairs damaged DNA and renders glioma cells resistant to alkylating agents." (PMID 23946790, 2013). "We sought to determine the frequency of aberrant promoter methylation and of chromosome 10 deletion and copy number alterations affecting the MGMT locus and to examine how those genomic alterations correlated with transcript levels in high-grade gliomas." (PMID 23505468, 2013). "MGMT downregulation in high-grade gliomas (HGG) has been mostly attributed to aberrant promoter methylation and is associated with increased sensitivity to alkylating agent-based chemotherapy." (PMID 23505468, 2013). "A wide spectrum of human tumors displays MGMT hypermethylation, including gliomas, lymphomas, colon cancer, head and neck cancer, testicular cancer, and retinoblastoma." (PMID 23505468, 2013). "MGMT promoter methylation has been used as a biomarker to predict the sensitivity of gliomas to DNA alkylating chemotherapeutics." (PMID 23946790, 2013). "MGMT hypermethylation is the best independent predictor of glioma patients’ response to alkylating agents, such as temozolomide." (PMID 24202337, 2013). "MGMT is involved in the repair of DNA damage and the prevention of second-level DNA damage, thus rendering glioma cells resistant to DNA alkylating agents." (PMID 23946790, 2013). "The majority of studies have focused on MGMT expression in high-grade gliomas, but few have explored MGMT expression in the other grades." (PMID 23946790, 2013). "The expression of MGMT was increased in the high-grade gliomas (62.1%) compared with the low-grade gliomas (46.2%), suggesting that the majority of gliomas (particularly malignant gliomas) are not sensitive to chemotherapy." (PMID 23946790, 2013). "Two genes have been shown to be especially robust biomarkers of glioma prognosis - methylguanine-DNA-methyltransferase (MGMT) and isocitrate dehydrogenase 1 (IDH1)." (PMID 23638004, 2013). "The vast majority of previous studies of MGMT promoter methylation in gliomas have used gel based methylation-specific PCR (MSP), which is a qualitative and time-consuming method." (PMID 22390413, 2012). "While lower expression of MGMT is desired in glioma cells for better TMZ efficacy, successful immune response in MG patients depends upon the functional efficiency of MGMT in conferring resistance to TMZ cytotoxicity." (PMID 23133490, 2012). "SATB1 expression was also positively correlated with Ki67 expression but negatively with MGMT promoter methylation in glioma tissues." (PMID 22839214, 2012). "It seems that EGFR and MGMT promoter hypermethylations are early events in the clonal evolution of gliomas and this gene inactivation has proved to be stable even in tumour recurrence." (PMID 22264301, 2012). "Correlation analysis showed the expression of SATB1 is correlated with MGMT promoter methylation which is a key prognostic factor and can predict treatment response in glioma." (PMID 22839214, 2012). "Due to its high prognostic and predictive relevance, assessment of the MGMT status has become state-of-the-art in current and planned clinical trials in glioma as a prognosticator, to stratify patients or even to limit trial entry accordingly." (PMID 22428052, 2012).
glioma (continued). "In our opinion, MGMT promoter methylation analysis gives sufficient prognostic information to merit its inclusion in the standard management of patients with high-grade gliomas, and in this study pyrosequencing came across as the better analytical method." (PMID 22390413, 2012). "In the present study, we report MGMT promoter methylation frequencies in gliomas determined by qMSP (low-grade gliomas 26% and high-grade gliomas 37%) as well as by pyrosequencing (low-grade gliomas 97% and high-grade gliomas 55%)." (PMID 22390413, 2012). "Univariate Cox regression analysis also identified that clinical variables including the pathological grade of glioma, SATB1 expression and MGMT promoter methylation were significantly associated with overall survival." (PMID 22839214, 2012). "There has been considerable and long-held enthusiasm to use MGMT as a predictive biomarker for glioma patients, with the longer term hope for its use as a marker to assign therapy to individual patients." (PMID 23346075, 2012). "Although various molecular markers involved in chemotherapy resistance have been investigated, their direct roles in the chemosensitivity and prognostic value of gliomas, except MGMT (O6-methylguanine DNA methyltransferase), remain controversial." (PMID 22741575, 2012). "Of great interest, the principal and novel finding of the current study is that a global DNA methylation surrogate, LINE-1 methylation, is positively proportional to the MGMT promoter methylation in gliomas." (PMID 21829728, 2011). "We examined the level of LINE-1 methylation in comparison with that of MGMT promoter methylation in glioma patients." (PMID 21829728, 2011). "In fact, the inconsistency between promoter methylation and protein expression assessed by IHC in gliomas is not limited to the MGMT gene, but has also been observed for other genes such as PTEN." (PMID 21269507, 2011). "Expression profiling of CD133+ glioma TSC demonstrates a 32-fold increase in the level of MGMT transcripts relative to CD133- tumor cells and indicates that this resistance mechanism is highly active in the glioma TSC population." (PMID 24212632, 2011). "In fact, MGMT status has recently been recommended as a stratifying factor for patients in glioma trials." (PMID 21269507, 2011). "Both MGMT status at protein level and promoter methylation have been correlated with prognosis and chemosensitivity in glioma patients." (PMID 21269507, 2011). "The promoter hypermethylation and epigenetic silencing of the O6-methylguanine-DNA methyltransferase (MGMT) gene have been often described in glioma." (PMID 21962230, 2011). "Gliomas are heterogeneous tumours and intratumoural heterogeneity of MGMT staining and methylation is a well-known event." (PMID 21269507, 2011). "Molecular and epigenetic characterization of gliomas is essential in future glioma therapy to develop individual therapeutic strategies and to overcome the MGMT mediated chemoresistance." (PMID 20122270, 2010). "Another aspect of many techniques is that differences in MGMT status between individual cells cannot be detected, even though several studies have shown the intratumoural heterogeneity of human gliomas for MGMT protein expression." (PMID 20517307, 2010). "In some instances, hypermethylation of certain TSG promoters predicts the response of tumors to therapy, as is the case with MGMT hypermethylation and response of primary gliomas to 1,2-bis(2-chloroethyl)-1-nitrosourea (BCNU) and temozolomide." (PMID 20520817, 2010). "Methylation of the MGMT promoter, a frequent phenomenon, makes gliomas more sensitive to alkylating agents by reducing gene expression." (PMID 18506188, 2008). "Cilengitide inhibited proliferation and induced apoptosis in glioma cells with methylated MGMT promotor when given alone or in combination with temozolomide." (PMID 19114005, 2008).
glioma (continued). "Several teams have reported this increased chemosensitivity for various types of gliomas and MGMT status, either methylation or level of expression, has become a predictive marker of chemosensitivity." (PMID 18506188, 2008). "The model tested the following covariates: age, glioma gene signature, and expression status of MGMT, VEGF, and EGFR." (PMID 18940004, 2008). "Taken together, these results suggest additive activity of cilengitide combined with TMZ in glioma cells with methylated MGMT promotor." (PMID 19114005, 2008). "We next studied the effect of temozolomide (TMZ) in combination with cilengitide on glioma cellls with methylated MGMT promotor." (PMID 19114005, 2008). "We established glioma models by transforming normal human astrocyte cells via retroviral-mediated gene transfer of defined genetic elements and found that MGMT was downregulated in the transformed cells." (PMID 17547775, 2007). "In gliomas, methylation of the O6-methylguanine-DNA methyltransferase (MGMT) gene promoter is a predictor of patients' responsiveness to alkylating agents." (PMID 17592497, 2007). "Functional studies showed that FLG knockdown increased GSC-associated markers (Oct4, 2.1-fold; SOX2, 1.8-fold) and enhanced TMZ resistance, whereas cp8 treatment reduced MGMT protein expression by 68% and significantly decreased glioma sphere size by 54% (p < 0.01)." (PMID 41943081, 2026). "In contrast, proneural tumors frequently harbor PDGFRA amplification or IDH1 mutations; the latter are characteristic of IDH-mutant gliomas and are associated with the CpG island methylator phenotype (G-CIMP), frequent MGMT promoter methylation, and comparatively favorable clinical outcomes." (PMID 41596524, 2026). "QX302 exhibits significantly greater potency (approximately 2.37-fold) in MGMT-/MMR- glioma U87 cells compared to MGMT-/MMR+ glioma U251 cells, suggesting that MMR deficiency may play a role in conferring moderate resistance to QX302." (PMID 41513607, 2026). "To fill this gap, we integrated the PANoScore with multiple clinical factors, including tumor grade, IDH status, 1p19q status, and the MGMT promoter status, and developed a PANoptosis-related risk score (PANo-RRS) via multivariate Cox analysis in the TCGA-Glioma cohort." (PMID 39901195, 2025). "Among tumor genetic mutations, IDH1 mutations and MGMT methylation are negatively correlated with the occurrence of VTE, and these two genetic mutations have also been proven to be negatively correlated with the occurrence of VTE in adult gliomas." (PMID 40873733, 2025). "Therefore, we aim to develop a reproducible, calibrated, and interpretable multiregional radiomics model that can be a valuable tool for predicting MGMT status in pre-operative glioma patients." (PMID 41584616, 2025). "First, patients biopsied when the rhythm in Mgmt methylation is low (during the late afternoon or night) may be getting a diagnosis of MGMT-unmethylated glioma even though they would have been diagnosed as an MGMT-methylated glioma with another biopsy time." (PMID 40909807, 2025). "Long‐term follow‐up substantiated this, though MGMT methylation does not define diagnostic glioma subtypes itself." (PMID 40792048, 2025). "The presents study is the first aiming to evaluate whether the novel imaging technique intraoperative hyperspectral imaging (HSI) can predict MGMT promoter methylation status in glioma patients using a novel optical scoring system." (PMID 41247617, 2025). "Methylation of the MGMT promoter is utilized as a biomarker to predict clinical response to a chemotherapeutic agent in glioma.With regard to MYO1G, cg10673833 located on MYO1G promoter region was reported to be a biomarker in the diagnosis and disease monitoring of colorectal cancer." (PMID 40556672, 2025).